NPC1 (NPC intracellular cholesterol transporter 1)
Diseases named in the same sentence as NPC1 in open-access papers (continued):
Sharing a sentence is not in itself a finding about the gene and the disease.
melanoma (4 papers, 2017 to 2024). A malignant, usually aggressive tumor composed of atypical, neoplastic melanocytes. "In analogy to TPC2, Rab7a knockdown in NPC1 cells exacerbates cholesterol accumulation, and in melanoma cells, Rab7a levels are significantly higher than in healthy skin melanocytes, impacting melanoma proliferation and invasion." (PMID 39682251, 2024). "Inhibiting cholesterol transport protein NPC1 using Leelamine led to a significant reduction in melanoma growth and metastasis." (PMID 35408842, 2022). "It has been reported that targeting NPC1 using Leelamine reduced cholesterol metabolism and melanoma tumour development by disrupting the transport or release of external cholesterol from lysosomes into the cellular pool." (PMID 35408842, 2022). "We first generated Sec24c, Gcc2, Rab14 and Npc1 pooled CRISPR-KO B16 melanoma cells and implanted them in C57BL/6 wild-type mice." (PMID 36379959, 2022). "Presence of the polar amino group in both compounds, led to similar predicted binding interactions (hydrophobic and H-bond contacts) in both NPC1 and NPC2 active sites, as evidenced by similar anti-melanoma activity of 4a." (PMID 28423677, 2017).
multiple sclerosis (4 papers, 2019 to 2022). A progressive autoimmune disorder affecting the central nervous system resulting in demyelination. "Metabolites of the sphingolipid metabolism, like MC and SM, are major components in the white matter, that are interesting especially regarding neurodegenerative diseases like NPC1 or multiple sclerosis." (PMID 32599915, 2020). "Sarah Spiegel’s group first showed evidence that FTY720/ fingolimod, so far used for treatment of multiple sclerosis, accumulates in the CNS when orally applied and is able to elevate NPC1 expression." (PMID 31248418, 2019). "To examine this with respect to MGAT5, we analyzed 111 NPC1 patients for two MGAT5 SNPs associated with multiple sclerosis; however, we did not identify an association with NPC1 phenotypic severity." (PMID 35563467, 2022). "In analogy to the known GCIP degeneration in multiple sclerosis, one might speculate that the atrophy of the ganglion cells in NPC1 could be at least be partly explained by inflammatory processes." (PMID 32222928, 2020).
Stroke (4 papers, 2012 to 2022). Sudden impairment of blood flow to a part of the brain due to occlusion or rupture of an artery to the brain. "The rod microglia observed in Npc1−/− mice were very large, extending beyond the size of multiple amoeboid microglia and therefore appear much larger than those reported in stroke." (PMID 22198570, 2012). "Better understanding the role of calcium signaling in platelets is important, as both NPC1 and Tangier patients have decreased plasma HDL‐C cholesterol levels, which are associated with an increased risk for all forms of atherosclerotic diseases, including myocardial infarction and stroke." (PMID 33204596, 2020).
anemia (3 papers, 2020 to 2023). A reduction in the number of red blood cells, the amount of hemoglobin, and/or the volume of packed red blood cells. "Although only some NPC1 patient erythrocyte phenotypes were altered, they were less acute than those of the mouse model and tended towards the lower end of the normal range, consistent with possible susceptibility to anemia." (PMID 37065726, 2022). "Further investigation of npc1 morphants revealed thrombocytopenia and mild anemia, in accord with the hematological presentation found in some NPC1 patients." (PMID 32435656, 2020). "Npc1-/- mouse erythrocytes were microcytic and exhibited significantly decreased MCV and HCT, features that have been documented for iron deficiency anemia, thalassemia and anemia of chronic diseases." (PMID 37065726, 2022).
Cerebellar atrophy (3 papers, 2021 to 2024). Cerebellar atrophy is defined as a cerebellum with initially normal structures, in a posterior fossa with normal size, which displays enlarged fissures (interfolial spaces) in comparison to the foliae secondary to loss of tissue. "Interestingly, in Npc1−/− mice, treatment with bimoclomol prevented cerebellar atrophy and preserved cerebellar weights at wild-type weights (p = 0.025; two-way ANOVA), whereas this improvement was blocked by co-administration with saracatinib." (PMID 36455410, 2022).
cognitive decline (3 papers, 2019 to 2025). "In NPC1 models of NP disease, cholesterol and sphingolipids accumulate in lysosomes and the trans-Golgi network, disrupting vesicle trafficking and triggering APP misprocessing, tau abnormalities, and cognitive decline." (PMID 41278977, 2025).
coronary heart disease (3 papers, 2010 to 2024). "In smokers, however, both in recessive model (GG vs. AA+AG) and additive model (GG vs. AG vs. AA) NPC1 G carriers showed decreased coronary heart disease risk compared with A carriers." (PMID 20955564, 2010). "The aim of this study was to look at the association and linkage between the NPC1 gene polymorphism and coronary heart disease in a Chinese population." (PMID 20955564, 2010). "The results of the present study suggest that NPC1 variants seem to be contributors to coronary heart disease occurrence in Chinese population." (PMID 20955564, 2010). "This study aims to investigate whether the genetic variation in NPC1 is associated with risk of coronary heart disease (CHD) and to detect whether NPC1 might interact with smoking on the risk of CHD." (PMID 20955564, 2010). "Moreover, in smokers, carriers of NPC1 GG had a decrease risk of coronary heart disease as compared with those carrying AA and AG." (PMID 20955564, 2010). "Therefore, considering the essential role in the atherosclerotic progression, one of the major pathological bases of coronary heart disease, dysregulation of NPC1 may be a risk factor that influences SCD development." (PMID 35480314, 2022). "Moreover, in smokers, NPC1 variants seem to confer protection to coronary heart disease." (PMID 20955564, 2010).
GM1 gangliosidosis (3 papers, 2009 to 2020). A rare lysosomal storage disorder characterized biochemically by deficient beta-galactosidase activity and clinically by a wide range of variable neurovisceral, ophthalmological and dysmorphic features. "Indeed, one of such defects, synaptic pathology is a common feature for several animal models of LSD, including feline models of GM1 gangliosidosis, mouse model of NPC1 disease, the Twitcher mouse, the natural mouse model of Krabbe disease and others." (PMID 32106459, 2020).
HIV-1 infection (3 papers, 2012 to 2024). The type species of lentivirus and the etiologic agent of acquired immunodeficiency syndrome (AIDS). "In support of this notion, overexpression of the lysosomal cholesterol transporter NPC1 partially relieved bafilomycin A1 inhibition of HIV-1 infection." (PMID 39339852, 2024). "NPC1 protein expression could also be decreased upon HIV-1 infection in a manner similar to ABCA1 downregulation." (PMID 22273177, 2012). "Thus, the decrease in NPC1 expression in NPCD55 cells after infection with HIV-1 was unexpected since sterol response genes are upregulated after HIV-1 infection." (PMID 22273177, 2012). "Negative regulatory factor (Nef), an auxiliary protein of HIV-1, was shown to trigger genes involved in cholesterol synthesis and homeostasis, suggesting that NPC1 might be a therapeutic target for treating HIV-1 infections, which rely heavily on host cell cholesterol levels." (PMID 38098077, 2023). "Downregulation of NPC1 protein expression may occur like that of ABCA1 post-HIV-1 infection." (PMID 38098077, 2023). "Therefore, the decreased expression of NPC1 could be miR33-mediated via induction of SREBP expression upon HIV-1 infection of NPCD55 cells." (PMID 22273177, 2012). "We transiently expressed NPC1-GFP in TZM-bl cells and then tested the impact NPC1-GFP expression on HIV-1 infection under conditions of bafilomycin A1 treatment." (PMID 39339852, 2024). "Since HIV-1 infection of NPCD55 cells induces sterol regulatory element-binding protein-1 (SREBP) expression, miR33 may be responsible for the reduced expression of NPC1." (PMID 38098077, 2023). "It is not clear why NPC1 expression was lost after HIV-1 infection of NPCD55 cells." (PMID 22273177, 2012).
Infertility (3 papers, 2017 to 2022). "Mice with a spontaneous mutation in the Npc1 have been described as infertile." (PMID 36614015, 2022). "Mutation of the cholesteryl transport protein Npc1 triggers infertility in mice." (PMID 27920259, 2017). "The findings indicate that the infertility of Npc1−/− mice are reflected in the morphology." (PMID 36614015, 2022).
liver dysfunction (3 papers, 2018 to 2022). "NPC1 is suspected based on clinical symptoms, such as severe liver dysfunction with hepatosplenomegaly in infancy and neurological symptoms." (PMID 33256498, 2021). "In neonatal NPC1 patients, cholestatic jaundice and liver dysfunction occur frequently; while some neonatal patients exhibit transient hepatosplenomegaly that resolves by 4 months of age, up to 10% of others exhibit rapidly progressing liver dysfunction that is fatal." (PMID 35140266, 2022).
liver fibrosis (3 papers, 2017 to 2021). "When we used the filter “Toxicity function” to identify changes related to hepatotoxicity, we found that many DEPs participate in liver fibrosis, necrosis, and depletion of glutathione, confirming that NPC1 deficiency induces liver damage." (PMID 34440927, 2021). "These increased levels of several amino acids likely arose from the liver parenchyma necrosis associated with hepatic fibrosis, a common feature in NPC1 liver in the mouse model." (PMID 28740230, 2017). "However, both NPC1 and NPC2 were significantly up-regulated in biopsies from patients with liver fibrosis (F1-2) compared with patients without fibrosis." (PMID 29522534, 2018).
ovarian carcinoma (3 papers, 2023 to 2025). A malignant neoplasm originating from the surface ovarian epithelium. "Supporting the role of NPC1 in invasion, 5 μM U18666A treatment of ErbB2 positive ovarian cancer organoids, whose invasive growth is dependent on full-length ErbB2, resulted in complete inhibition of invasive growth." (PMID 37420029, 2023).
Tangier disease (3 papers, 2020 to 2023). "The pathogenic cascade in NPC1 has been previously been shown to be triggered by the storage of sphingosine, suggesting that it is likely that the cellular pathology we observe in Tangier disease is also due to sphingosine storage." (PMID 31707734, 2020). "It had previously been shown that levels of NPC1 increase in Tangier disease cells, potentially in an attempt to rebalance cholesterol transport pathways when ABCA1 is deficient." (PMID 37844193, 2023). "Although the precise mechanism leading to the secondary induction of NPC cellular phenotypes in Tangier disease cells remains to be determined, this unexpected finding reinforces the links between NPC1 and ABCA1 function." (PMID 37844193, 2023). "When we measured levels of NPC1 and NPC2 in Tangier disease cells by western blotting we found there to be variation between the patients." (PMID 31707734, 2020).
tauopathies (3 papers, 2012 to 2024). "Thus, pathogenic NPC1 and NPC2 mutations are the causative agents for NPC but do not represent a general risk factor for other tauopathies." (PMID 38554150, 2024).
alpha-synucleinopathies (2 papers, 2023 to 2025). "It has been found that NPC1 gene variants might represent a risk or susceptibility factor in the development of alpha-synucleinopathies such as multiple system atrophy." (PMID 40106490, 2025).
Anxiety (2 papers, 2019 to 2024). Intense feelings of nervousness, tension, or panic often arise in response to interpersonal stresses. "Npc1+/+ mice: Total walking distance and relative center distance in the open field test are linked to explorative locomotor activity and anxiety-related behavior." (PMID 39081805, 2024). "Npc1−/− mice: In Npc1−/− mice, neither treatment resulted in significant changes in anxiety-related behavior, as evidenced by only non-significant differences in relative center times in the open field tests." (PMID 39081805, 2024).
aortic atherosclerosis (2 papers, 2022 to 2024). A atherosclerosis that involves the aorta. "In addition to that, NPC1 deficient mice can reconstitute with LDL receptor and accelerated aortic atherosclerosis was observed in the NPC1−/− macrophages.Furthermore, NPC1 repression was found to invoke lipid accumulation in human macrophages exposed to environmental aryl hydrocarbons." (PMID 35480314, 2022).
cerebellar degeneration (2 papers, 2020 to 2021). Degeneration of the cerebellum. "Strikingly, lack of AnxA6 in NPC1-deficient animals (Npc1−/−/Anxa6−/−) did not prevent cerebellar degeneration." (PMID 33810523, 2021). "In addition, NPC1-deficient cells experience increased toxicity with oxidative stress, a known inducer of LMP, and NPC mice deficient in cystatin B, an inhibitor of cathepsins, exhibit exacerbated cerebellar degeneration." (PMID 32931479, 2020).
clear cell renal cell carcinoma (2 papers, 2024 to 2025). "Similar increases in NPC1 expression have been observed in clear cell renal cell carcinoma (ccRCC) and gastric cancer (GC), where high NPC1 expression correlated with an unfavorable prognosis." (PMID 40881173, 2025). "Our studies elucidated the role of NPC1 as a potential therapeutic target in clear cell renal cell carcinoma (ccRCC)." (PMID 38339268, 2024).
esophageal adenocarcinoma (2 papers, 2021 to 2024). A malignant tumor with glandular differentiation arising predominantly from Barrett mucosa in the lower third of the esophagus. "In a cohort of 55 patients, two biopsies of esophageal adenocarcinomas exhibited a novel fusion gene as a result of a complex interchromosomal translocation of NPC1 and maternal embryonic leucine zipper kinase (MELK)." (PMID 34281263, 2021). "Additionally, fusion transcripts such as FGFR2-GAB2 and NPC1-MELK have shown potential as diagnostic markers and therapeutic targets in esophageal adenocarcinoma." (PMID 39857631, 2024). "Research showed a weak connection between esophageal adenocarcinoma and NPC1." (PMID 34281263, 2021).
fibrosis (2 papers, 2018 to 2020). the formation of excess fibrous connective tissue in an organ or tissue in a reparative or reactive process. "Livers of patients with fibrosis (all F1 apart from 1 patient whom was F2) had up-regulations of PPARG (20%), INSIG1 (39%), SRB1 (11%), NPC1 (13%), and NPC2 (30%) (all P < 0.05)." (PMID 29522534, 2018). "Co-cultures of PHH1 and NPC1, which spontaneously and reproducibly deposited fibrillary extracellular matrix exemplified by COL1A1 staining, were used as a screening platform for anti-NASH/fibrosis drugs." (PMID 32295224, 2020).
glioma (2 papers, 2020 to 2024). A benign or malignant brain and spinal cord tumor that arises from glial cells (astrocytes, oligodendrocytes, ependymal cells). "MAPK3 and CX3CL1 were strongly positive; NFE2L2, HSP90AB1, and SUPT20H were moderately positive; and FKBP1B, BIRC5, NPC1, IKBKE, BID, and PTEN were weakly positive in glioma tissue relative to their expression levels in normal tissue." (PMID 33194668, 2020). "Other glioma cell clusters exhibited MES2-, AC-, OPC-, and NPC1/2-like cell states." (PMID 39333557, 2024).
Gliosis (2 papers, 2014 to 2017). Gliosis is the focal proliferation of glial cells in the central nervous system. "We found that gliosis is an intrinsic feature of this model system, reflecting one of the pathological distinguishing marks of NPC1." (PMID 28841900, 2017). "Gliosis is a common feature for ongoing neurodegeneration and plays an important role in pathologies of NPC1 disease." (PMID 25472750, 2014).
Granuloma (2 papers, 2017 to 2022). A compact, organized collection of mature mononuclear phagocytes, which may be but is not necessarily accompanied by accessory features such as necrosis. "The identified variant in NPC1 can contribute to increasing the risk of developing CD and granulomas." (PMID 35741735, 2022). "We identify a group of patients with NPC1 mutations who develop severe early-onset CD-like intestinal inflammation with granuloma formation and perianal disease that cannot be distinguished from CD." (PMID 26953272, 2017).
Impaired glucose tolerance (2 papers, 2011 to 2015). An abnormal resistance to glucose, i.e., a reduction in the ability to maintain glucose levels in the blood stream within normal limits following oral or intravenous administration of glucose. "Therefore, the NPC1 polymorphisms at select loci are believed to adversely affect NPC1 protein function and predispose to either weight gain or impaired glucose tolerance depending on race/ethnicity, especially when combined with an obesogenic or diabetogenic environment." (PMID 26120596, 2015).
interstitial lung disease (2 papers, 2019 to 2022). A diverse group of lung diseases that affect the lung parenchyma. "Interestingly, the common features of clinical presentation and radiological findings in NPC1 patients with pre/perinatal onset from two recent studies indicate that these patients develop pulmonary complications that are consistent with interstitial lung disease." (PMID 31861571, 2019).
iron deficiency (2 papers, 2022 to 2023). "A probable consequence of iron deficiency in the NPC1 brain is compromised in mitochondrial function and capacity resulting in reduced oxidate energy and further neuronal dysfunction." (PMID 37065726, 2022). "Furthermore, mitochondrial changes were noted in NPC1-deficient auditory cells, which is also consistent with a functional iron deficiency." (PMID 37998376, 2023). "In NPC1-deficient auditory cells, iron levels increased but the levels of both the transcript and protein for the transferrin cellular receptor increased, indicating that the cells were trying to acquire additional iron consistent with a functional iron deficiency." (PMID 37998376, 2023). "This profile includes elements characteristic of both inflammatory and non-inflammatory iron deficiencies, which to our knowledge is unique to NPC1." (PMID 37065726, 2022).
lung carcinoma (2 papers, 2021 to 2025). "SARS-CoV-2-induced ACE2 and NPC1 elevation may have a negative influence on the immune responses of LUSC and CD8+T infiltration of LUAD, and negatively affect the sensitivity of anti-lung cancer drugs." (PMID 35082790, 2021).
lung disease (2 papers, 2013 to 2021). "Thus, the NPC1 mutant feline demonstrated lung disease with pathological manifestations comparable to those seen in mice." (PMID 23843985, 2013). "The NPC1 and NPC2 pulmonary diseases were compared to determine whether any pathologic characteristics differed between them." (PMID 23843985, 2013). "Our study, using histological, immunological and biochemical procedures, demonstrates that the absence of NPC1 and NPC2 proteins in the lungs of mutant mice on a BALB/c background results in lung disease." (PMID 23843985, 2013).
mental disorder (2 papers, 2022 to 2023). A disease that has its basis in the disruption of mental process. "Niemann-Pick type C (NPC, ORPHA: 646) is a neuro-visceral, psychiatric disease caused predominantly by pathogenic variants in the NPC1 gene or seldom in NPC2." (PMID 38002933, 2023). "There have been some studies of NPCD on the effect of NPC1 deficiency and mental disorders." (PMID 35936782, 2022).
morbid obesity (2 papers, 2022 to 2023). An excess of body weight, normally defined as an individual with a body mass index greater than 35 or a body weight greater than one hundred percent of ideal body weight. "For example, mutations in NPC1 have been linked to early-onset and morbid obesity in adulthood." (PMID 36414820, 2023).